MPO (myeloperoxidase)
Diseases named in the same sentence as MPO in open-access papers (continued):
Sharing a sentence is not in itself a finding about the gene and the disease.
septic shock (9 papers, 2017 to 2024). Shock caused by infection; frequently caused by gram negative bacteria, although some cases have been caused by other bacteria, viruses, fungi, and protozoa; characterized by fever, chills, tachycardia, tachypnea, and hypotension. "The amounts of plasma dsDNA and MPO-DNA complexes were significantly higher in septic shock patients than those in healthy controls." (PMID 32600436, 2020). "NET components (dsDNA and MPO-DNA complexes) were significantly increased in response to treatment with septic shock patient-derived exosomes and correlated positively with disease severity and outcome." (PMID 32600436, 2020). "On days 1, 3, and 7 of septic shock, the plasma MPO-DNA level was significantly higher in the patients compared with the healthy volunteers." (PMID 30005596, 2018). "Surrogate markers of NETs (cfDNA, nucleosomes and MPO-DNA complexes) have been identified in the plasma of septic patients and in murine models of lipopolysaccharide (LPS)-induced septic shock." (PMID 28161762, 2017). "Direct evidence of the presence of NETs in bloodstream is lacking, but histones (or nucleosomes), free DNA and myeloperoxidase could be detected in plasma and are significantly increased in septic shock-induced DIC." (PMID 29197958, 2017).
Arrhythmia (8 papers, 2017 to 2025). Any cardiac rhythm other than the normal sinus rhythm. "The link between MPO and AF has been previously demonstrated, with elevated levels found in patients with paroxysmal AF, and increases the risk of arrhythmia recurrence after ablation." (PMID 40002559, 2025). "Increased circulating MPO levels in MI patients at the time of admission are associated with increased in-hospital rates of arrhythmias, as well as re-infarction and death." (PMID 39061857, 2024). "According to Li and colleagues, higher levels of MPO might be predictive of arrhythmia recurrence after AF ablation." (PMID 35651726, 2022).
chronic rhinosinusitis (8 papers, 2015 to 2025). Chronic form of sinusitis. "AE in chronic rhinosinusitis with nasal polyps (CRSwNP) was associated with increased expression of mucus cytokines including myeloperoxidase (percentage increase [PI] = 101%), IL-5 (PI = 125%), and IL-6 (PI = 162%) and could be predicted by the increasing mucus cystatin and periostin." (PMID 32811568, 2020). "If some of the patients had chronic sinusitis, they could be reconsidered as having GPA (MPO-positive)." (PMID 33301468, 2020).
multiple myeloma (8 papers, 2019 to 2025). "The GG genotype was also found to be associated with an increasing amount of serum MPO in chronic lymphocytic leukemia and multiple myeloma." (PMID 40806204, 2025). "While encouraging, complete eradication of MM tumour was not achieved, prompting future studies utilising current anti‐myeloma therapies in combination with MPO inhibitors." (PMID 37699574, 2023). "Infections are a common complication in patients with multiple myeloma, and high expression of MPO might prevent severe infections in individuals with multiple myeloma." (PMID 38919521, 2024). "Activated myeloid cell populations are increased in multiple myeloma (MM); however, the functional consequences of myeloid‐derived MPO within the myeloma microenvironment are unknown." (PMID 37699574, 2023). "Importantly, the therapeutic targeting of MPO with the irreversible inhibitor 4‐ABAH, impedes myeloma disease progression in vivo." (PMID 37699574, 2023). "MPO modifies the bone marrow microenvironment with increases in IL6, VEGFa and CCL2 stromal expression, and a reduction in IFN‐γ positive cytotoxic T‐cells, providing a supportive niche for myeloma plasma cell growth." (PMID 37699574, 2023). "Notably, these patients exhibit positive myeloperoxidase (MPO) antibodies, and a common feature is the confirmation of multiple myeloma (MM) independent of kidney pathology." (PMID 39058808, 2024).
multiple system atrophy (8 papers, 2013 to 2024). Multiple system atrophy (MSA) is a neurodegenerative disorder characterized by autonomic failure (cardiovascular and/or urinary), parkinsonism, cerebellar impairment and corticospinal signs with a median survival of 6-9 years. "Verdiperstat, another MPO inhibitor, is being developed for the treatment of neurodegenerative diseases such as multiple system atrophy (MSA) and amyotrophic lateral sclerosis (ALS)." (PMID 36982778, 2023). "Pharmacological inhibition of MPO reduced the severity of clinical symptoms and tissue damage in brain and improved survival in a mouse model of MS and multiple system atrophy." (PMID 23691142, 2013). "Indeed, the irreversible MPO inhibitor AZD3241 improved the clinical outcome in a mice study for chronic inflammatory bowel disease but failed for treatment in multiple system atrophy." (PMID 38001789, 2023).
nasal polyps (8 papers, 2015 to 2025). "This patient had nasal polyps and elevated eosinophils, but the myeloperoxidase–anti-neutrophil cytoplasmic antibody (MPO-ANCA) was negative." (PMID 38919941, 2024). "We found that MPO levels increased in nasal polyps, but the ECP and total IgE levels of the serum and tissues did not." (PMID 35075349, 2022). "Here, we preliminarily differentiated the subtypes of CRSwNP by measuring the levels of eosinophil cationic protein (ECP) and myeloperoxidase (MPO) in nasal polyps." (PMID 35075349, 2022). "The nasal polyp groups had higher MPO activities than controls." (PMID 35075349, 2022). "The CRSwNP group showed significantly elevated MPO activity, PI3K, p-AKT protein, HIF-1α, and IL-17A mRNA levels in nasal polyps." (PMID 35075349, 2022). "Neutrophils (MPO+) were the prominent infiltrating inflammatory cell in nasal polyps of smokers and nonsmokers." (PMID 30040868, 2018).
parasitemia (8 papers, 2018 to 2026). "To examine neutrophil activation in the context of parasite infection and Mcpt4 deficiency, we examined levels of plasma myeloperoxidase (MPO) and neutrophil elastase (NE), antimicrobial effectors frequently used as markers for neutrophil activation." (PMID 35154114, 2022). "We analyzed fecal MPO levels to study their association with parasitic infections." (PMID 33886672, 2021). "MPO, sCD25 and sCD14 were significantly correlated with clinical disease severity and sCD25 and in particular MPO were also strongly associated with degree of parasitemia as assessed by quantitative P. falciparum PCR in plasma." (PMID 30563486, 2018). "Bacterial 16S copies were negatively correlated with MPO and Mcpt4 outside of the core network, which was mainly driven by parasitemia." (PMID 38780542, 2024). "Eotaxin was positively correlated with NE and plasma RANTES (CCL5), IL-1α, and IL-2, and strongly negatively correlated with MPO, Mcpt1, parasitemia, plasma IL-4, ileal MCs, and FITC-dextran." (PMID 38780542, 2024). "By 10 days PI in Mcpt4-/- mice, NE was positively correlated with IL-17, which was negatively correlated with parasitemia, while MPO in Mcpt4+/+ mice was positively correlated with parasitemia." (PMID 35154114, 2022). "We observed a strong correlation between the total number of parasitic infections in each child and MPO levels (ng/mL) at 24 months in stool specimens from that child (r = 0.95, P = 0.001), however, we did not notice any correlation at 3 and 12 months." (PMID 33886672, 2021). "sCD163, sCD25 and in particular MPO correlated with the degree of parasitemia as assessed by qPCR." (PMID 30563486, 2018). "Participants with parasitic infections had higher median values of MPO, NEO and AAT." (PMID 30133067, 2018). "Placental levels of MPO, MMP9, and PRTN3 all positively correlate with placental parasitemia as well as placental hemozoin bearing WBCs, suggesting that production is enhanced by chronic infection." (PMID 34737733, 2021). "In baso IL-4/IL-13 (+) mice, FITC-dextran levels were positively correlated with MPO, NE, Mcpt1, and parasitemia in the main network, and bacterial 16S copies were negatively correlated with plasma IL-12p40, which was isolated from the main network." (PMID 38780542, 2024). "In Mcpt4+/+ mice, parasitemia is the overwhelming focal point of the host immune response, with correlations between type 1 (IFN-γ) and type 2 (IL-10 and IL-13) cytokines and chemokines as well as MPO." (PMID 35154114, 2022). "Increased levels of circulating myeloperoxidase were observed at 6 and 10 days PI in Mcpt4+/+ but not Mcpt4-/- mice, affirming a role for neutrophil activation that was not predictive of parasitemia or bacterial 16S copies in blood." (PMID 35154114, 2022). "SCD163, sCD25 and in particular MPO levels, but not sCD14 levels, were strongly correlated with the degree of parasitemia." (PMID 30563486, 2018). "Herein we show a strong association between MPO levels and the degree of P. falciparum parasitemia as assessed by qPCR analyses, suggesting that neutrophils and MPO could promote rather than attenuate parasitemia." (PMID 30563486, 2018).
preeclampsia (8 papers, 2017 to 2025). Preeclampsia is a hypertensive disorder of pregnancy that is characterized by new-onset hypertension with proteinuria presenting after 20 weeks of gestation, and depending on mild or severe forms may initially present with severe headache, visual disturbances, and hyperreflexia. "Nonetheless, we observed an association between the c.–765T>C (rs2243828) polymorphism and MPO levels in patients with gestational hypertension, as well as a link between the g.9890A>C (rs2071409) variant and MPO concentrations in the same group." (PMID 40806204, 2025). "Nevertheless, our data indicate that the ‘C, C’ haplotype may offer protection against preeclampsia, potentially due to its association with reduced MPO levels." (PMID 40806204, 2025). "The immunohistochemical study found more CD68+ monocytes/macrophages and myeloperoxidase (MPO)+ Granu in the placenta of the “immunological” preeclampsia subtype." (PMID 37854606, 2023). "In our study we compared 60 cases and 120 matched controls, which to our knowledge is one of the biggest studies carried out in relation to MPO and preeclampsia." (PMID 30976066, 2019). "In this study, we showed a significant increase in MPO in cases as early as 20 weeks’ gestation when compared with controls and this significant increase was equally evident at time of disease in preeclampsia." (PMID 30976066, 2019). "Although we were the first to investigate MPO predictive potential in preeclampsia by measuring both concentration and activity in two different matrices (plasma and urine), this study present some limitations." (PMID 28860607, 2017). "Here we examined myeloperoxidase concentration and activity in plasma and urine samples from pregnant women who remained normotensive throughout pregnancy and those who developed preeclampsia in order to assess its potential to predict this disorder." (PMID 28860607, 2017). "It is plausible that individuals with gestational hypertension (GH) or PE who carry certain MPO genotypes or haplotypes may exhibit differing levels of plasma MPO." (PMID 40806204, 2025). "The extent to which PM and PM/HIV coinfection may contribute to preeclampsia via MPO production or modification of other neutrophil functions remains to be determined." (PMID 34737733, 2021). "To our knowledge, we are the first to investigate the potential of MPO for preeclampsia prediction." (PMID 28860607, 2017). "The variation in MPO levels in previous preeclampsia studies may be due to small sample size." (PMID 30976066, 2019). "In conclusion, this study did not found any evidence that MPO, concentration or activity, was elevated before the diagnosis of preeclampsia, probably because the MPO increase might happen as a result from proinflammatory stimulus after the establishment of the disease." (PMID 28860607, 2017). "Therefore, this study aimed to explore MPO concentration and activity in both plasma and urine samples from pregnant women before preeclampsia onset, in order to verify if this enzyme is a potential biomarker for preeclampsia diagnosis." (PMID 28860607, 2017). "In preeclampsia patients, neutrophils are activated with oxidized lipids generated by the placenta which inducing ROS, TNF-α, and myeloperoxidase (MPO), harming the vascular endothelium." (PMID 37475854, 2023). "For instance, elevated NET biomarkers, such as myeloperoxidase-DNA (MPO-DNA) complexes, Neutrophil Elastase (NE), and citrullinated histone H3 (citH3), are observed in preeclampsia and spontaneous preterm birth, correlating with placental inflammation and vascular dysfunction." (PMID 41000384, 2025). "Similarly, there was no statistical significance at each time-point when comparing expression of calprotectin, MPO and MMP8 in preterm preeclampsia versus term preeclampsia." (PMID 30976066, 2019). "Myeloperoxidase is a proinflammatory enzyme found to be increased in patients with established preeclampsia but never investigated before the disease onset." (PMID 28860607, 2017).
preeclampsia (continued). "Myeloperoxidase did not seem to have a potential application for preeclampsia prediction." (PMID 28860607, 2017). "Therefore, in view of the results, MPO does not seem to display a potential use as a marker for preeclampsia prediction." (PMID 28860607, 2017). "Although no statistical differences has been found in MPO parameters between control and cases, a decreasing trend can be observed in urine MPO concentration and in plasma MPO activity on patients with severe preeclampsia." (PMID 28860607, 2017). "While investigating plasma MPO concentration and activity no statistical differences were observed among subjects who remained normotensive throughout pregnancy (controls) and those who developed any of the two forms of preeclampsia (mild and severe cases) (P = 0.6 and P = 0.2, respectively)." (PMID 28860607, 2017).
purpura (8 papers, 2019 to 2025). A small blood vessel hemorrhage into the skin and/or mucous membranes. "In these studies, MPO-ANCA-positive patients had higher frequencies of vasculitic manifestations (purpura, renal involvement, and peripheral neuropathy), whereas MPO-ANCA-negative patients more often exhibited eosinophilic manifestations (cardiac involvement and gastrointestinal symptoms)." (PMID 40572776, 2025). "However, purpura were scattered, and the titer of antimyeloperoxidase-antineutrophil cytoplasmic antibodies (MPO-ANCA) was high." (PMID 33505756, 2021). "Furthermore, a cutaneous-limited form of MPO-ANCA-positive MPA has been reported, characterized by recurrent crops of purpura over weeks to months." (PMID 41179045, 2025).
scleroderma (8 papers, 2008 to 2024). Scleroderma is a rare autoimmune connective tissue disorder characterized by abnormal hardening of the skin and, sometimes, other organs. "Reports from Japan describe patients with long-standing scleroderma and myeloperoxidase ANCA positive normotensive crescentic GN." (PMID 18474117, 2008). "In this study, the authors observed that MPO-DNA complexes were significantly more concentrated in the plasma of patients with an early and active scleroderma pattern compared with those with a late scleroderma pattern in capillaroscopy." (PMID 32645862, 2020). "A study indicates that enriched genes including MPO (myeloperoxidase), RXFP1, CXCL11, CTNND2, BMPR2, TLR3, CCR2, and CAV1 are altered expressed in scleroderma." (PMID 38137330, 2023). "Demographic characteristics including gender, race, disease subtype and age of scleroderma onset were similar between anti-MPO-positive and anti-MPO-negative groups." (PMID 30764870, 2019).
sinusitis (8 papers, 2015 to 2025). An acute or chronic inflammatory process affecting the mucous membranes of any sinus cavity. "Furthermore, sinusitis was more likely to be associated with elevated MPO-ANCA levels (adjusted hazard ratio: 2.59, 95% CI: 1.14–5.92; P = 0.024)." (PMID 33301468, 2020). "The presence of concurrent sinusitis, positive MPO-IgG antibody, and clinical symptoms consistent with AAV allowed a clinical diagnosis without tissue biopsy." (PMID 40859493, 2025). "Complete sinus CT imaging revealed sinusitis, and anti-myeloperoxidase IgG (MPO-IgG) antibody was positive." (PMID 40859493, 2025). "The study identified a significant association between the presence of sinusitis and a relapse in patients with MPA and elevated MPO-ANCA levels, even after adjusting for clinically relevant risk factors." (PMID 33301468, 2020). "We aimed to evaluate the relationship between sinusitis, the relapse thereof, and the increased myeloperoxidase (MPO)-ANCA levels in MPA patients in Japan." (PMID 33301468, 2020). "In conclusion, sinusitis was associated with a higher risk of relapse and elevated MPO-ANCA levels in MPA patients, suggesting that careful management may be required to reduce the risk of relapse in patients with sinusitis." (PMID 33301468, 2020). "In addition, MPO is a marker of cell activation in acute sinusitis." (PMID 38077338, 2023). "This study identified that sinusitis carries a higher risk of relapse in AAV and that ANCA levels increase in patients with MPO-positive MPA, suggesting that careful management may be required in patients with sinusitis at presentation to reduce the risk of AAV relapse." (PMID 33301468, 2020). "Persistent symptoms despite antibiotic therapy, a positive anti-myeloperoxidase (MPO-IgG) antibody test, and concurrent sinusitis raised suspicion for AAV, which was confirmed through multidisciplinary consultation." (PMID 40859493, 2025). "Of the 74 patients with negative conversion of MPO-ANCA levels, 30 (40.5%) patients had increased MPO-ANCA levels (14 [82.4%], sinusitis; 16 [28.1%], non-sinusitis; P < 0.001)." (PMID 33301468, 2020). "In the present study, we identified a significant relationship between sinusitis and the subsequent increase in MPO-ANCA levels, suggesting that sinusitis itself may be a trigger for ANCA production and a predisposing factor for relapse in AAV." (PMID 33301468, 2020).
Thrombocytopenia (8 papers, 2019 to 2024). A reduction in the number of circulating thrombocytes. "Thrombocytopenia led to a significant reduction in intratumor PAI-1, MMP-3, MMP-9, and MPO, specifically in B16F1 tumors." (PMID 38493157, 2024). "In mild-grade CLP, clopidogrel- and vehicle-treated mice did not display a significant decrease in MAP, while thrombocytopenia and plasma concentrations of TNFα, IL6, IL10, MPO, TAT and organ damage reached similar levels in both groups, although lower than those reached in the high grade CLP." (PMID 34447900, 2021).